IL6ST (interleukin 6 cytokine family signal transducer)
Diseases named in the same sentence as IL6ST in open-access papers (continued):
Sharing a sentence is not in itself a finding about the gene and the disease.
infection (12 papers, 2007 to 2025). The state of being infected such as from the introduction of a foreign agent such as serum, vaccine, antigenic substance or organism. "Upon infection of unvaccinated mice, the initial expression of Il6 on day 1 p.i. was upregulated, like that of Il6st, whereas that of Il6ra was significantly downregulated." (PMID 40243929, 2025). "The correlation between IL23A and IL6ST was only seen after infection with BCM-300 and P1 strains (P<.05)." (PMID 24069393, 2013). "The increased phosphorylation of the IL6ST (gp130) receptor throughout the initial 24 hours of infection with Salmonella may be an immunometabolic signature of the instigation of the innate immune response." (PMID 35846741, 2022). "The upregulation of IL6ST and EBI3 was less pronounced after infection compared to that of IL8 and IL23A." (PMID 24069393, 2013). "Gene expression analysis demonstrated a strong upregulation of IL23A (encodes p19) by infection, whereas IL23R, Epstein–Barr virus-induced gene 3 (EBI3), IL6ST, IL12A, and IL27RA were found to be expressed, but not regulated, or to a lesser extent." (PMID 24069393, 2013).
bacterial infection (3 papers, 2024 to 2025). "Besides, IL6 was related to bacterial infection and inflammation response, correlated IL6ST was reported to elevate when COPD aggravates." (PMID 39091676, 2024).
cardiovascular disease (2 papers, 2017 to 2021). "Further evidence for the role of sgp130 in the onset of cardiovascular disease has been reported in studies on genetic variants located in the gene coding gp130 (IL6ST)." (PMID 28250574, 2017).
adenocarcinoma (1 paper, 2021). A common cancer characterized by the presence of malignant glandular cells. "Introduction of a knock-in gp130/IL6ST mutation was shown to cause hyperactivation of STAT3 through the disruption of a negative feedback mechanism, leading to the promotion of the development of adenocarcinomas." (PMID 34834425, 2021).
retinopathy (1 paper, 2016). "Therefore, the retinopathy-associated increase in IL6ST and OSMR detected here may be a result of STAT1/3-mediated transcriptional activation." (PMID 27242532, 2016).
IL6ST also shares sentences with these, for which no sentence is quoted: Arthritis (8 papers); atherosclerosis (6); coronary artery disease (6); Crohn disease (5); hyper-IgE syndrome (4); myocardial infarction (4); Anxiety (3); systemic lupus erythematosus (3); AIDS (2); arterial hypertension (2); atrial fibrillation (2); coronary atherosclerosis (2); diabetes (2); eczema (2); eosinophilia (2); gastric adenocarcinoma (2); inflammation (2); ischemic stroke (2); Kaposi's sarcoma (2); Kawasaki disease (2); liver fibrosis (2); lymphoma (2); neurodevelopmental disorder (2); pneumonia (2); psoriasis (2); achondroplasia (1); acute lymphoblastic leukemia (1); adrenal cancers (1); autoimmune disease of the nervous system (1); B-cell lymphomas (1).
A further 73 diseases each share a sentence with IL6ST in 1 paper.